PCDH10 (protocadherin 10)
Diseases named in the same sentence as PCDH10 in open-access papers (continued):
Sharing a sentence is not in itself a finding about the gene and the disease.
tumor (50 papers, 2012 to 2026). "Ras association domain family 1, form A (RASSF1A), and protocadherin 10 (PCDH10) are tumor suppressor genes." (PMID 38184573, 2024). "Pcdh10 has also been implicated in a range of human cancers, acting as a tumor suppressor and playing key roles in regulating tumor growth, invasion and metastasis." (PMID 37058252, 2023). "In the present study, PCDH10 overexpression significantly decreased the expression of genes associated with tumor progression and metastasis, including EREG, MMP1, MMP9, TGFB1, RASA4, and CXCL8, in GC cells." (PMID 37147733, 2023). "Up-regulation of CXCR4 and KIT is associated with leukemic blasts and PCDH10 is a common tumor suppressor that is also epigenetically silenced in hematopoietic malignancies." (PMID 30575819, 2019). "Notably, PCDH10 expression was negatively associated with the number of lymph node metastasis (p = 0.029; pN stage) and tumor size (p = 0.043) in GC." (PMID 37147733, 2023). "Likewise, PCDH10 promoter methylation was significantly associated with tumor recurrence and shortened survival of patients with bladder transitional cell carcinoma." (PMID 35468745, 2022). "Importantly, tumor-associated PCDH10 silencing may be quite useful for early detection of occurrence and/or progression of multiple human cancers." (PMID 35468745, 2022). "This study investigated the molecular basis of the tumor-suppressive role of the classic protocadherin tumor suppressor PCDH10 in breast carcinogenesis." (PMID 41608634, 2026). "Elevated HOTAIR levels can inhibit the activity of tumor suppressors such as protocadherin 10 (PCDH10), progesterone receptor (PGR), protocadherin β5 (PCDHB5), and junctional adhesion molecule 2 (JAM2), leading to tumorigenesis." (PMID 40129920, 2025). "Particularly, PCDH10 expression decreased in tumor tissues with increasing number of metastatic lymph node in patients with GC (42.9% for pN0-1 patients, 28.6% for pN2 patients, 21.4% for N3a patients, 7.1% for N3b patients)." (PMID 37147733, 2023). "For example, PCDH10 was directly engaged in the negative regulation of the epidermal growth factor receptor signaling pathway, resulting in tumor suppression." (PMID 37147733, 2023). "Previous studies revealed that ectopic expression of PCDH10 suppressed cancer cell malignancy in vitro and restrained tumor growth and metastasis in vivo, substantiating its tumor suppressive roles." (PMID 37147733, 2023). "Numerous studies have reported that Pcdh10 acts as a tumor suppressor in a wide range of human tumors." (PMID 37058252, 2023). "Pcdh10 methylation detected in plasma increases with increasing methylation rate in tumor tissues only in early CRC (stage I/II)." (PMID 37058252, 2023). "It has been reported that human PCDH10, located at chromosome 4q28.3, is frequently inactivated in various human cancers suggesting that PCDH10 acts as tumor suppressor in these malignancies." (PMID 35468745, 2022). "Our model contributes to scrutinizing the complex molecular mechanisms of tumor initiation and progression upon PCDH10 silencing in many human cancers." (PMID 35468745, 2022). "For both tumor types, ablation of either all or only long isoforms of Pcdh10 aggravated the disease." (PMID 35468745, 2022). "In former studies, the inactivation of PCDH10 has been demonstrated in many different human tumor types, and was often found to be important for tumor progression and poor survival." (PMID 35468745, 2022). "A new mouse model was generated allowing for the first time to examine the remarkable tumor suppression activity of protocadherin-10 in vivo." (PMID 35468745, 2022). "in case of WT Pcdh10 (Pcdh10+/+), tumor formation was dependent on GFAP-Cre driven Rb ablation; iii." (PMID 35468745, 2022). "Research has shown that the ectopic expression of PCDH10 strongly inhibits tumour cell growth, migration, invasion, and colony formation." (PMID 36291586, 2022).
tumor (continued). "In summary, we present here exclusive data strongly supporting the concept of PCDH10 being an important tumor suppressor in human malignancies." (PMID 35468745, 2022). "shorter tumor lag period and increased fraction of animals affected in case of heterozygous and in particular homozygous ablation of all Pcdh10 isoforms." (PMID 35468745, 2022). "Re-expression experiments have consolidated the importance of PCDH10 expression in tumor suppression." (PMID 35468745, 2022). "in case of Pcdh10all ablation, tumor formation was significantly more efficient than in case of WT Pcdh10; iv." (PMID 35468745, 2022). "By informatics analysis, we identified three tumor suppressor genes: DACH1, PCDH10 and SMAD4, all of which were negatively associated with FOXM1 and validated as functionally relevant targets of miR-552." (PMID 33867818, 2021). "PCDH10, a member of the non‐clustered protocadherin subfamily, was reported for suppressing tumour in multiple cancers because of its promoter CpG hypermethylation." (PMID 34841662, 2021). "All these findings indicated that PCDH10 was a tumour suppressor gene through regulating the function of hsa_circ_0001666 on the proliferation, apoptosis as well as invasion of CRC cells." (PMID 34841662, 2021). "PCDH10 is repressed by promoter hypermethylation in multiple cancers and functions as a tumour suppressor gene." (PMID 34841662, 2021). "A PCDH10 é um supressor de tumor gástrico; sua metilação nas fases iniciais da carcinogênese gástrica é um fator prognóstico independente." (PMID 33369468, 2020). "The ectopic expression of PCDH10, when silenced by methylation, can suppress tumor cell growth, migration, invasion, and colony formation." (PMID 33369468, 2020). "Low PCDH10 expression correlates with tumor size, TNM stage, smoking status, and alcohol consumption pattern." (PMID 33369468, 2020). "Hypermethylation in gene promoters is a general epigenetic modification in cancer formation, especially for inhibition of tumor-suppressive genes such as PCDH10, DKK1, and KLF4." (PMID 32701143, 2020). "Our group previously reported the first evidence that PCDH10 acts as a novel broad TSG that strongly suppresses tumor cell growth, migration, invasion, and colony formation." (PMID 32089740, 2020). "PCDH10 methylation detected in plasma increased with increasing methylation rate in tumor tissues only in early stage cancers, while this correlation was apparently lost in advanced stages." (PMID 33369468, 2020). "Intriguingly, expression of PCDH7 and PCDH10, which are generally considered to be tumor suppressor genes, has been proven necessary for the tumorigenicity of non-small cell lung cancer and glioblastoma, respectively." (PMID 32694982, 2020). "PCDH10 has been recently indicated as a tumor suppressor gene due to its role in cell cycle, tumor progression and metastasis." (PMID 31390840, 2019). "PCDH10 isconsidered as a tumor suppressor gene, suppressingdifferent tumors including leukemia, lung, esophageal,colorectal and breast cancers." (PMID 30507090, 2019). "Several studies also revealed that PCDH10 (protocadherin 10) is calcium dependent cell adhesion molecule which suppresses tumor in gastric epithelial hypermethylated in H. pylori associated GC and EBV-infected individual." (PMID 28421114, 2017). "Several studies have concluded that PCDH10 suppresses tumor cell growth, migration, invasion, and colony formation, and is frequently inactivated epigenetically in colorectal, cervical, nasopharyngeal, esophageal, and other cancer types 27,26,28." (PMID 26276761, 2015). "Notable examples include E-Cadherin (CDH1), T-Cadherin (CDH13) and Proto-Cadherin 10 (PCDH10) which are recognized tumor-suppressor genes, and have been found to be hypermethylated in a number of human cancers." (PMID 23419152, 2013).
tumor (continued). "In this study, we found that PCDH10, located at an important tumor suppressor locus 4q28.3, was totally silenced in KM3 and RPMI-8226 cell lines, but widely expressed in normal adult bone samples." (PMID 22245948, 2012). "Through the effect of PCDH10 in CAM angiogenic assays, we found the PCDH10 acts as a novel tumor suppressor gene involved in angiogenesis." (PMID 22245948, 2012). "Additionally, allelic loss of Pcdh10 was ascertained in primary CRC tumors, and highly related with tumor progression and distant metastasis, suggesting that its allelic loss predicts an adverse prognosis." (PMID 37058252, 2023). "Protocadherin 10 plays a critical role in the central nervous system including in cell adhesion, formation and maintenance of neural circuits and synapses, regulation of actin assembly, cognitive function and tumor suppression." (PMID 37058252, 2023). "Several molecular mechanisms have been proposed for the tumor suppressive role of PCDH10." (PMID 37147733, 2023). "Additionally, Pcdh10 is a newly discovered tumor suppressor gene which is downregulated by hypermethylation or genetic deletion in various malignant tumors, and is linked to the occurrence, proliferation, invasion and metastasis of tumors." (PMID 37058252, 2023). "Pcdh10 is well-known as a tumor suppressor in colorectal carcinogenesis, invasion and metastasis." (PMID 37058252, 2023). "In addition, aberrant methylations of Pcdh10 have been recognized as a non-invasive biomarker for tumor diagnosis and prognosis." (PMID 37058252, 2023). "Moreover, Pcdh10-mediated tumor suppression can apparently follow different and complex signalling pathways in various tumor cell systems." (PMID 35468745, 2022). "Also in case of ablation of only long Pcdh10 isoforms, a statistically significant decrease in tumor-free survival was observed." (PMID 35468745, 2022). "PCDH10 is frequently inactivated in epigenetic processes in various cancers, suggesting that it may act as a tumour suppressor gene; however, the specific mechanism by which cadherin-23 and PCDH10 affect cancer cells remains unclear." (PMID 36291586, 2022). "However, the causality between auricular tumor formation and GFAP-Cre mediated Pcdh10 ablation was further strengthened in the following ways: i." (PMID 35468745, 2022). "In addition to numerous studies on the cell biological consequences of PCDH10 re-expression or silencing in tumor cell lines, this is the first report of a proven tumor suppressor effect of Pcdh10 in an in vivo model." (PMID 35468745, 2022). "Functional studies revealed that PCDH10 could inhibit cell proliferation, migration, as well as induce tumour cells apoptosis." (PMID 34841662, 2021). "Furthermore, HOTAIR induces methylation of PCDH10 (Protocadherin 10), a tumor suppressor gene, in GIST cells." (PMID 34576322, 2021). "PCDH10 belongs to the non-clustered protocadherin protein family encoding calcium-dependent adhesion protein and is known as a tumor suppressor gene in many tumors." (PMID 33867818, 2021). "Methylation could occur in PCDH8, PCDH10, and PCDH17 in both PC tumor tissue and serum, and is associated with poor prognosis and shorter biochemical relapse-free survival." (PMID 33369468, 2020). "Little is known about the functions of PCDHs, but some members, such as PCDH8 and PCDH10, have been shown to suppress tumor activity, suggesting that PCDHs may act as tumor suppressors by influencing tumor growth and metastasis." (PMID 31526370, 2019). "The frequent silencing of PCDH10 in cancer is ascribed to the aberrant hypermethylation of its promoter and, consequently, altered signal transduction, resulting in the failure to suppress invasion and tumor progression." (PMID 27659532, 2016).
tumor (continued). "Two weeks after transfection and subsequent selection of drug resistant colonies, the numbers of colonies produced by PCDH10-transfected cells was significantly less than that by empty vector-transfected cells, suggesting that PCDH10 does suppress the colony formation of tumor cells." (PMID 22245948, 2012). "Interestingly, we found protocadherin 10 (PCDH10) is one of these 9 tumor suppressor genes." (PMID 26871474, 2016). "Our results show that PCDH10, an important member of the cadherin family, may directly induce several pro-angiogenic molecules in the microenvironment, and plays a positive role in inhibiting tumor angiogenesis." (PMID 22245948, 2012). "Mechanistically, PCDH10 enhanced GSK-3β phosphorylation at Try216, inhibited aberrant β-catenin activation and upregulated the expression of the tumor-suppressive nuclear envelope protein LMNA expression through direct binding." (PMID 41608634, 2026). "In the course of EEC, the PCDH10–Wnt/β-catenin–MALAT1 regulatory axis is a crucial component, and protocadherin 10 (PCDH10), a tumor suppressor gene, decreases the level of MALAT1, which is correlated with the inhibition of tumorigenesis." (PMID 38674413, 2024). "A novel PCDH10-Wnt/β-catenin-MALAT1 regulatory axis that contributes to ECC development and progression, delays tumor growth and induces cell apoptosis." (PMID 37058252, 2023). "In contrast, two members of the protocadherin tumor suppressor family‐PCDH9 and PCDH10‐were down‐regulated in high B7‐H3 expressers." (PMID 34562306, 2021). "Previous reports have shown the tumor suppressive roles of DACH1, PCDH10 and SMAD4 in tumorigenesis 24-26." (PMID 33867818, 2021). "Multiple studies link the overexpression or silencing of ncPcdhs (PCDH8, PCDH10, PCDH18, PCDH20) in primary tumors and tumor cell lines to reduced or increased levels of phosphorylated GSK3β, respectively." (PMID 32694982, 2020). "Particularly, MALAT1 has been identified as a functional downstream target of Protocadherin 10 (PCDH10), a tumour suppressor protein, down-regulated in EEC." (PMID 30037059, 2018). "Protocadherin 10 (PCDH10), a tumor suppressor, was found to negatively regulate telomerase activity through interaction with hTERT." (PMID 28587243, 2017). "To explore the mechanism behind the antitumor activity of grifolin, we performed a screening of genes related to tumor adhesion/invasion regulation, including MMP1,2,3,9,19, TIMP-1,2,3, CD44, CDH1 and PCDH10." (PMID 27626695, 2016). "Concordantly hypermethylated CpGs were associated with genes involved in Cadherin, Wnt and Notch signaling pathways, many of which have been previously reported as frequently methylated in a variety of neoplasms, such as APC2, SFRP2, CDH13, CDH15 and PCDH10." (PMID 22737091, 2012). "Conversely, TQ treatment resulted in the downregulation of several genes overexpressed in GBM cells, including potential oncogenes like AEBP1, MIAT, GHR, LMO1, ELF3, and genes involved in tumor proliferation and migration such as EPHA4, COL3A1, PCDH10, ROBO1, ADAMTS5, PCDH18, ST8SIA1." (PMID 39874307, 2025). "PCDH10 displayed full or partial promoter methylation in tumor tissues, whereas little or no methylation was observed in the adjacent nontumor tissues." (PMID 37147733, 2023). "From this and RNA-Seq data of these cell families, we conclude that, at least in this cancer model, the short isoform of Pcdh10 is a major effector of tumor suppressor activity, what has not been reported before." (PMID 35468745, 2022). "Despite lacking several conserved motifs, the short isoform of Pcdh10 was fully active as tumor suppressor." (PMID 35468745, 2022). "Thus, PCDH acts as a tumor suppressor in CRC and plays a role in the restriction of liver metastasis; PCDH10 methylation can be detected in patient’s blood circulation." (PMID 33369468, 2020). "PCDH10, PCDH17 and PCDH20 expression levels were downregulated in this neoplasm." (PMID 33369468, 2020).
tumor (continued). "PCDH10, one of the non-clustered protocadherins, is identified as a tumor suppressor gene in many tumors." (PMID 29202805, 2017). "To evaluate the role of PCDH10 as a tumor suppressor gene (TSG) in MM, we thus sought to establish whether ectopic expression of PCDH10 could inhibit tumor cell clonogenicity." (PMID 22245948, 2012). "Although PCDH10 protein expression was observed mainly in the cytoplasm of GC cells and adjacent nontumor tissues, its expression was significantly lower (χ2 = 34.954, p < 0.001) in GC tumor tissues than in adjacent nontumor tissues." (PMID 37147733, 2023). "Similarly, a recent study revealed an oncogenic transcription factor FOXM1 which activated expression of miR-552, and further inhibited downstream target genes including Pcdh10, DACH1 and SMAD, which in turn promoted tumor progression and resulted in poor prognosis in PC patients." (PMID 37058252, 2023). "An animal model for the tumor suppressor activity of PCDH10 has not been reported." (PMID 35468745, 2022). "The frequent silencing of PCDH10 in MM cell lines, compared with its broad expression in normal tissues, suggests that PCDH10 might have tumor suppressor function." (PMID 22245948, 2012). "PCDH10, a member of the non-clustered protocadherin family δ2 subtype, has recently been shown to inhibit the growth, migration, invasion, and colony formation of tumor cells, and may act as a tumor suppressor gene involved in tumorigenesis." (PMID 40255484, 2025). "In addition to tumor inhibition, methylation of Pcdh10 may serve as a non-invasive biomarker for CRC diagnosis as Pcdh10 methylation that is present in tissues could be detected in serum/plasma." (PMID 37058252, 2023). "Because the short isoform of Pcdh10 lacks several conserved sequences (CM1, CM2, WIRS) it indicates that these regions are not essential for tumor suppression." (PMID 35468745, 2022).